PDCD1 (programmed cell death 1)
Diseases named in the same sentence as PDCD1 in open-access papers (continued):
Sharing a sentence is not in itself a finding about the gene and the disease.
cancer (continued). "Based on miRDB and miRabel databases, the recent Bioinformatic Exploratory Study identified 49 unique miRNA were identified across fourteen different cancers as potentially targeting PD-1 (PDCD1)/PD-L1 (CD274)." (PMID 36189271, 2022). "Immune checkpoint inhibitors, including anti-programmed cell death 1 (PD-1) antibody, provide improved clinical outcome in certain cancers." (PMID 36212775, 2022). "The programmed cell death-1 (PD-1) and programmed death ligand-1 (PD-L1) inhibitors are immune checkpoint inhibitors (ICPs) that block the cancer cell's ability to evade the tumor-specific cytotoxic T lymphocytes (CTLs)." (PMID 35720783, 2022). "Programmed cell death 1 (PD‐1) membrane proteins were expressed on the EV surface while maintaining the ability to bind to ligand proteins and ligand‐expressing cancer cells." (PMID 35384397, 2022). "Therapeutic antibodies targeting immune checkpoint molecules, such as programmed cell death 1 (PD-1) and its ligand PD-ligand 1 (PD-L1), have shown great promise in cancer treatment, by reinvigorating immune responses against cancers." (PMID 33580183, 2021). "The development of immuno-oncology (IO) therapeutics has changed the way we treat many cancers, most dramatically with inhibitors of programmed cell death-1 (PD-1), its ligand (PD-L1) and cytotoxic T-lymphocyte-associated antigen (CTLA-4)." (PMID 33816286, 2021). "Recently, immune checkpoint inhibitors (ICIs), such as anti-programmed cell death-1 (PD-1) or programmed cell death ligand-1 (PD-L1) monoclonal antibodies, have improved the overall survival (OS) of various types of cancers, including AGC." (PMID 34306002, 2021). "The cytotoxic T lymphocyte antigen 4 (CTLA4) or programmed cell death 1 (PD-1)/PD-1 ligand 1 (PD-L1) axis is approved for use in a variety of cancer types." (PMID 34326876, 2021). "The dependence of cancer on these pathways has been therapeutically exploited with the development of specific immune checkpoint inhibitors (ICI) such as anti-programmed cell death 1 (anti-PD-1) and anti-PD-1 ligand (anti-PD-L1) antibodies." (PMID 33916915, 2021). "Monoclonal antibodies that block the interaction between programmed cell death 1 (PD-1) and its ligand (PD-L1) have revolutionized cancer immunotherapy." (PMID 34324079, 2021). "By targeting the immune checkpoint in TME, anti-cytotoxic T-lymphocyte associated protein 4 (CTLA4), anti-programmed cell death 1 (PD-1), and anti-CD274/PD-L1havebeen shown to be the most effective immunotherapy methods for cancer." (PMID 34827528, 2021). "Immune checkpoint blockade targeting PD-1 (PDCD1)/PD-L1 (CD274) is increasingly used for multiple cancers." (PMID 34067485, 2021). "To date, immune check-point inhibitors (ICIs), particularly inhibitors of programmed cell death-1 (PD-1) and PD ligand-1 (PD-L1) have become prominent in cancer treatment and also improved life expectancy of cancer patients." (PMID 34552581, 2021). "IL-18 had been shown to exert potential immunosuppressive effects in cancer by increasing expression of programmed cell death-1 (PD-1) on activated mature NK cells." (PMID 33718235, 2021). "In advanced cancer, various immune checkpoint inhibitors, including programmed cell death 1 (PD-1), its ligand PD-L1, and cytotoxic T-lymphocyte-associated antigen 4 (CTLA-4), have achieved promising oncological improvements." (PMID 34069461, 2021). "The primary intra-cellular checkpoint proteins that play a major role in cancer pathogenesis and division are the cytotoxic T-lymphocyte-associated antigen 4 (CTLA-4), and programmed cell death-1 (PD-1) checkpoints." (PMID 34221257, 2021). "Cancer immunotherapy using checkpoint inhibitors, such as anti-programmed cell death-1 (PD-1) and its ligand (PD-L1), has emerged as a new and powerful treatment option for several types of cancer." (PMID 34198859, 2021).
cancer (continued). "Immune checkpoints signals are negative regulators of effector T-cells, and the two mainly studied molecules in cancers are Cytotoxic T-Lymphocyte Associated Protein 4 (CTLA-4) and Programmed Cell Death 1 (PD-1)." (PMID 34771694, 2021). "The difference in clinical relevance of CD274 and PDCD1 points to the unique molecular biology of each individual cancer type and highlights a need to identify where the differences lie." (PMID 34067485, 2021). "Among the ICRs, programmed cell death 1 (PD-1) has mainly been antagonized to enhance the survival of human patients with cancer by restoring the function of tumor-infiltrating (TI) CD8+ T cells." (PMID 34901012, 2021). "Immune checkpoint inhibitors (ICIs) such as antibodies against programmed cell death 1 (PD-1) and programmed cell death ligand 1 (PD-L1), have shown remarkable efficacies in many subtypes of cancers." (PMID 34157799, 2021). "Programmed cell death protein 1 (PD1; also known as PDCD1) is highly expressed on Treg cells of various cancers, thereby suppressing T cell effector functions." (PMID 33796525, 2021). "Taken together, these results shed light on the varying PDCD1/CD274 networks between individual cancers and signpost a need for more cancer-specific investigations and treatments." (PMID 34067485, 2021). "Genes correlating with PDCD1/CD274 across multiple cancers were taken forward for drug repurposing via DRUGSURV and microRNA analysis using miRDB and miRabel." (PMID 34067485, 2021). "This study utilized a bioinformatic approach to explore potential factors contributing to the PDCD1/CD274 network on a pan-cancer basis." (PMID 34067485, 2021). "PDCD1, CD47 and CD94 inhibit the killing of cancer cells and are associated with B lymphocytes in many types of tumors." (PMID 33588924, 2021). "In the first clinical report of the use of SpCas9 to edit genes in human cells, three genes (TRAC, TRBC, and PDCD1) were subject to ex vivo editing in primary human T cells, which were subsequently expanded and infused into cancer patients." (PMID 34162850, 2021). "In cancer immunotherapy, an emerging approach is to block the interactions of programmed cell death-1 (PD-1) and programmed cell death-ligand 1 (PD-L1) using small-molecule inhibitors." (PMID 34681584, 2021). "Considering the profound roles of PDCD1/PDL1, cancer immunotherapy based on PDCD1/PDL1 checkpoint blockade has been developed to reinvigorate CD8+ T cells in advanced or refractory cancers." (PMID 33513276, 2021). "Recently, immune checkpoint inhibitors (ICIs) targeting immune checkpoints, especially programmed cell death-1 (PD-1) and its ligand (PD-L1), have shown encouraging results in several cancer types." (PMID 34761007, 2021). "Therapeutic blockade of the programmed cell death 1 (PD-1) immune checkpoint has provided durable clinical benefit to patients with advanced cancers." (PMID 34446728, 2021). "The commonly used immune checkpoint inhibitors in cancer therapies are designed for inhibiting receptors (e.g., programmed cell death-1 (PD-1) receptor) typically expressed in T-cells and the ligand (e.g., PD-L1) expressed by cancer cells." (PMID 34452059, 2021). "One of the best characterized immune checkpoints, and one of two unequivocally shown to operate in cancer cells, involves the interaction between programmed cell death-1 (PDCD1, often known as PD1) on the T cell and its ligand (CD274, often known as PD-L1)." (PMID 33578919, 2021). "In particular, the blockade of the Programmed cell death 1/Programmed cell death 1 − Ligand -1 (PD-1/PD-L1) axis in PD-L1-expressing cancers has yielded remarkable results." (PMID 34140620, 2021). "The inhibitory receptor programmed cell death-1 (PD-1) mediates functional defects in cytotoxic NK cells in various cancers." (PMID 34884723, 2021). "Immune checkpoint inhibitors targeting the programmed cell death-1 (PD-1) and its ligand PD-L1 have proven to be efficient cancer therapies in a subset of patients." (PMID 34201323, 2021).
cancer (continued). "The therapeutic potential of PD-1 blockade in cancer therapy was illustrated in Pdcd1-/- mice and then confirmed in cancer patients after anti-PD-L1 treatment." (PMID 35154081, 2021). "The programmed cell death-1 (PD-1) receptor and its ligands PD-L1 and PD-L2 are immune checkpoints that suppress anti-cancer immunity." (PMID 33413561, 2021). "A soluble form of programmed cell death-1 (PD-1) ligand (sPD-L1) has been found at increased levels in cancer and sustained inflammation, thereby deregulating immune functions." (PMID 34575296, 2021). "In this study, we utilized an immunodeficient NOG mouse substrain deficient for mouse FcγR genes, NOG-FcγR−/− mice, to evaluate the anti-cancer effects of nivolumab, an anti-programmed cell death-1 (PD-1) antibody." (PMID 34702924, 2021). "PDCD1 is an immune checkpoint and protects against autoimmune responses, and the interaction of PD‐L1 on cancer cells with PD1 on T cells leads the cancer cells to escape from immune system." (PMID 33591648, 2021). "Anti-programmed cell death-1 immune checkpoint therapy (aPD-1) is a cancer immunotherapy that has revolutionized cancer treatment regimens in recent years and is of interest for the treatment of complex keratinocyte carcinoma cases." (PMID 34944945, 2021). "Immunotherapy in the form of checkpoint blockade, such as anti-programmed cell death 1 (PD-1) monoclonal antibody pembrolizumab, targets and interferes with this interaction, thereby restoring T-cell ability to remove cancer cells." (PMID 34336422, 2021). "The recent success of therapeutic targeting of the immune checkpoint molecules, especially of programmed cell death 1 (PD-1) and programmed cell death ligand 1 (PD-L1), has changed the paradigm of treatment for several types of cancer." (PMID 34638944, 2021). "New checkpoint inhibitor-based immunotherapy, such as the use of programmed death one receptor (PD-1, CD279, or PDCD1) antibody Pembrolizumab (Pembro) has significantly improved the survival of lung and other cancer patients." (PMID 34406120, 2021). "Immune checkpoint inhibitors, such as cytotoxic T-lymphocyte antigen 4 inhibitors, programmed cell death 1 inhibitors and programmed cell death-ligand 1 inhibitors, have recently emerged as novel drugs in the anti-cancer therapy." (PMID 36046145, 2021). "Anti-programmed cell death-1 (PD-1)/programmed death ligand-1 (PD-L1) antibodies are administered in varied human cancer types." (PMID 33441183, 2021). "Similar to the striking differences observed with the CD274-correlated genes, there are again some differences with the PDCD1-correlated genes that are immediately apparent between cancers." (PMID 34067485, 2021). "Immune checkpoint inhibitors (ICIs), especially programmed cell death 1/programmed cell death ligand-1 (PD-1/PD-L1) inhibitors, have revolutionized the treatment landscape of various cancers." (PMID 34692478, 2021). "A similar pattern was seen for PDCD1 expression, with four of five cancers demonstrating that high PDCD1 expression was statistically significantly beneficial." (PMID 34067485, 2021). "Patient RNA-seq data from fifteen cancer types were accessed on cBioPortal to determine the role of PDCD1/CD274 in patient survival and to identify positively and negatively correlated genes, which were also assessed for clinical relevance." (PMID 34067485, 2021). "The results suggested that UBE2C expression was positively associated with the immune checkpoint-related genes in 31 cancers, which mainly included CD274, CTLA4, HAVCR2, LAG3, PDCD1, PDCD1LG2, SIGLEC15, and TIGIT." (PMID 34858987, 2021). "Programmed cell death 1 (PD-1)-based immunotherapy has revolutionized the treatment of various cancers." (PMID 33593825, 2021). "Immune checkpoint inhibitors such as antibodies to programmed cell death-1 (PD-1) have recently revolutionized treatment strategies for advanced cancer." (PMID 32050652, 2020).
cancer (continued). "Recently, immune checkpoint inhibitors (ICIs), including programmed cell death 1 (PD-1) inhibitors, such as nivolumab and pembrolizumab, have been shown to have promising effects in the treatment of various types of cancer." (PMID 32429323, 2020). "Frequency of genetic variants of CTLA-4, PDCD1, PD-L1, BTLA, HAVCR2, and LAG3 genes (in different human populations) for which the association with cancer risk has been investigated." (PMID 33519815, 2020). "Recent studies have suggested that immune checkpoints play an important role in the immune escape of cancer, so we further analysed the relationship between the 4 subtypes and 8 immune checkpoint genes (PDCD1, CD274, PDCD1LG2, CTLA4, CD86, CD80 and CD267)." (PMID 31995855, 2020). "Programmed cell death 1/programmed death ligand 1 (PD-1/PD-L1) inhibition boosts T cell function and is approved as a first-line therapy for various cancers, including non–small cell lung cancer." (PMID 32814713, 2020). "Currently, the availability of ICIs, such as anti-cytotoxic T lymphocyte antigen 4 (CTLA-4) and anti-programmed cell death 1(PD-1)/programmed cell death-ligand 1 monoclonal antibodies, has significantly changed the approach to cancer treatment." (PMID 32582554, 2020). "Direct cell–cell signaling, such as programmed cell death 1/programmed cell death ligand 1 signaling, or mechanical stress between cancer cells and other surrounding cells is important in the TME." (PMID 32931156, 2020). "Checkpoint inhibitors such as those targeting programmed cell death-1 (PD-1) are becoming widely used in cancer treatment regimens." (PMID 32183719, 2020). "PDCD1 (PD-1, Programmed Cell Death 1 Protein) has been found to be highly expressed in many cancers and was found to be responsible for the escaping of cancer cells from immunosurveillance." (PMID 33330048, 2020). "This review will summarize current knowledge about the impact of the genetic variants of CTLA-4, PDCD1, PD-L1, BTLA, TIM-3, and LAG-3 on cancer risk." (PMID 33519815, 2020). "Immune checkpoint inhibitors (ICIs) targeting cytotoxic T-lymphocyte antigen-4 (CTLA-4) or programmed cell death-1 (PD-1) pathways are reshaping the landscape of cancer therapy, yielding unprecedented clinical success in treating multiple cancer types." (PMID 32306958, 2020). "Immunotherapies blocking immune inhibitory receptors programmed cell death-1 (PD-1) and cytotoxic T-lymphocyte-associated protein-4 (CTLA-4) on T-cells have dramatically improved patient outcomes in a range of advanced cancers." (PMID 32992658, 2020). "Programmed cell death 1 (PD-1) blocking antibodies are effective against many types of cancer because of their ability to reinvigorate antitumor T-cell responses." (PMID 33030521, 2020). "Inhibitors that block the programmed cell death-1 (PD-1) pathway can potentiate endogenous antitumor immunity and have markedly improved cancer survival rates across a broad range of indications." (PMID 32457754, 2020). "The immune checkpoint molecules, programmed cell death-1 (PD-1) and its ligand programmed death-ligand-1 (PD-L1), regulate immune responses in cancer development." (PMID 32724483, 2020). "Both inhibitory of checkpoints (CTLA-4 and PDCD1) commonly seen on activated T-cells have been found to be the most reliable targets for the treatment of cancer." (PMID 33585210, 2020). "Recent trials have shown an overall survival (OS) benefit in 10-40% advanced cancer patients treated with programmed cell death 1 (PD-1) or programmed death-ligand 1 (PD-L1) inhibitors." (PMID 33488843, 2020). "Recently, immune checkpoint inhibitors (ICIs), such as anti-PD-1 (Programmed cell Death 1) and anti-CTLA 4 (cytotoxic T-lymphocyte-associated protein 4), have emerged as new targets for cancer treatment, and many clinical studies have been conducted." (PMID 33096708, 2020).
cancer (continued). "The efficacy of immunotherapies that use antibodies to block programmed cell death 1 (PD-1) or its ligand 1 (PD-L1) have been extensively investigated for a variety of cancer types." (PMID 31022941, 2019). "Programmed cell death 1 (PD-1) monoclonal antibodies have been approved by regulatory agencies for the treatment of various types of cancer, and the mechanism involves the restoration of T cell functions." (PMID 31780710, 2019). "Blockade of the programmed cell death 1 (PD-1)/programmed cell death-ligand 1 (PD-L1) interaction has emerged as a powerful strategy in cancer immunotherapy." (PMID 31455818, 2019). "The evasion of apoptosis always occurs in cancer, and many molecules, such as programmed cell death 1 (PD-1)–programmed cell death 1 ligand 1 (PDL1)/PDL2, BCL-2, caspase and NF-κB, are associated with the processes of apoptosis." (PMID 31462894, 2019). "In recent years, the checkpoint inhibitors targeted programmed cell death 1 (PD-1) and its ligand 1 (PD-1 ligand, PD-L1) achieved landmark significance in treating a variety of cancers including non-small cell lung cancer (NSCLC)." (PMID 31014442, 2019). "In the last decade, inhibitors targeting immune checkpoint molecules such as cytotoxic T-lymphocyte antigen 4 (CTLA-4), programmed cell death 1 (PD-1), and programmed cell death-ligand 1 (PD-L1) brought about a major paradigm shift in cancer treatment." (PMID 31192215, 2019). "Immune checkpoint inhibitors (ICIs) that target cytotoxic T lymphocyte antigen 4, programmed cell death-1, and PD-ligand 1 have revolutionized cancer treatment, achieving unprecedented efficacy in multiple malignancies." (PMID 31849640, 2019). "Inhibitors to interfere protein-protein interactions (PPI) between programmed cell death 1 (PD-1) and programmed death ligand-1 (PD-L1) block evasion of cancers from immune surveillance." (PMID 31723178, 2019). "A target for cancer immunotherapy is programmed cell death-1 (PD-1), which is a negative regulator of immune cytotoxicity that is expressed on immune cells, particularly T cells." (PMID 31443240, 2019). "Immune checkpoint inhibitors (ICIs) targeting programmed cell death 1 (PD-1) and its ligand, PD-L1, have been approved to treat various cancers." (PMID 31614877, 2019). "Recent advances in cancer treatment are emerging from new therapies that target T-cell inhibitory receptors, such as cytotoxic T-lymphocyte-associated antigen-4 (CTLA-4) and programmed cell death-1 (PD-1)." (PMID 31333652, 2019). "Further, one of the most relevant IR is programmed cell death 1 (PD-1), whose blockade reinvigorates T cells against various cancer types." (PMID 31708921, 2019). "The new immunotherapy targeting the programmed cell death 1 (PD-1) receptor and its cognate ligand PD-L1 has renewed hopes of eradicating the most difficult human cancers to treat." (PMID 30897754, 2019). "Three genes are involved in immune system response to cancer, which clearly indicates that they bear a protective role: PDCD1, KLRG1, and MUC16." (PMID 31568528, 2019). "Immunotherapy in the form of monoclonal antibodies (mAbs) targeting the programmed cell death 1 (PD-1)/programmed cell death-ligand 1 (PD-L1) axis have revolutionized the treatment for various cancer types." (PMID 31349612, 2019). "Programmed cell death 1 inhibitors have revolutionized therapy for cancer by their outstanding effectiveness." (PMID 31533865, 2019). "Recently, immunotherapies using antibodies against programmed cell death 1 (PD-1) and its ligand (PD-L1) have proven to be powerful and effective treatments for patients with various advanced cancers in many clinical trials." (PMID 31142289, 2019). "The interaction of PD-L1 with its counter-receptor programmed cell death-1 (PD-1) expressed by activated T lymphocytes, inhibits T-cell activation and proliferation, thus contributing to cancer immune evasion." (PMID 31583120, 2019).